RBL2 (RB transcriptional corepressor like 2)
Description:
Key regulator of entry into cell division. Directly involved in heterochromatin formation by maintaining overall chromatin structure and, in particular, that of constitutive heterochromatin by stabilizing histone methylation. Recruits and targets histone methyltransferases KMT5B and KMT5C, leading to epigenetic transcriptional repression. Controls histone H4 'Lys-20' trimethylation. Probably acts as a transcription repressor by recruiting chromatin-modifying enzymes to promoters. Potent inhibitor of E2F-mediated trans-activation, associates preferentially with E2F5. Binds to cyclins A and E. Binds to and may be involved in the transforming capacity of the adenovirus E1A protein. May act as a tumor suppressor.
Synonyms: p130; RB2; BRUWAG
Tractability: Small molecule: a structure with a bound ligand is known. PROTAC: ubiquitination databases record sites on it; its protein half-life has been measured.
Gene: Protein-coding gene on chromosome 16 (53,433,977 to 53,491,649, forward strand). Ensembl gene ENSG00000103479.
Subcellular location: Nucleus
Subcellular location (Human Protein Atlas): Mitotic chromosome; Nucleoli rim; Nucleoplasm; Cytosol
Pathways (Reactome):
Cell Cycle: Cyclin A:Cdk2-associated events at S phase entry; Cyclin D associated events in G1; Cyclin E associated events during G1/S transition; G0 and Early G1; G1/S-Specific Transcription; Transcription of E2F targets under negative control by DREAM complex; Transcription of E2F targets under negative control by p107 (RBL1) and p130 (RBL2) in complex with HDAC1
Gene expression (Transcription): FOXO-mediated transcription of cell cycle genes
Gene Ontology:
Molecular function: promoter-specific chromatin binding; protein binding; RNA polymerase II transcription regulatory region sequence-specific DNA binding; RNA polymerase II cis-regulatory region sequence-specific DNA binding
Biological process: negative regulation of gene expression; regulation of lipid kinase activity; negative regulation of DNA-templated transcription; negative regulation of G1/S transition of mitotic cell cycle; regulation of DNA-templated transcription; regulation of cell cycle; regulation of transcription by RNA polymerase II
Cellular component: extracellular exosome; nucleolus; nucleoplasm; chromatin; DRM complex; nucleus; transcription regulator complex
Genetic constraint (gnomAD): Loss-of-function variants: 46 observed, 97.69 expected, observed/expected ratio (o/e) 0.47, 90% interval 0.37 to 0.6. The upper end of that interval is the gene's LOEUF score, 0.6, which puts it in group 2 of 6, group 1 being the genes least tolerant of losing a copy. Missense variants: 1,103 observed, 1,258.8 expected, observed/expected ratio (o/e) 0.88, 90% interval 0.83 to 0.92. Synonymous variants: 414 observed, 437.3 expected, observed/expected ratio (o/e) 0.95, 90% interval 0.87 to 1.03.
Homologues: Orthologues: chimpanzee RBL2 (99% identical), macaque RBL2 (99% identical), dog RBL2 (97% identical), pig RBL2 (97% identical), rabbit RBL2 (96% identical), guinea pig RBL2 (91% identical), mouse Rbl2 (91% identical), rat Rbl2 (90% identical), tropical clawed frog rbl2 (65% identical), zebrafish rbl2 (60% identical), Drosophila melanogaster Rbf (24% identical), Caenorhabditis elegans lin-35 (19% identical), and 1 more. Paralogues in human: RBL1 (49% identical), RB1 (23% identical).
Diseases named in the same sentence as RBL2 in open-access papers:
RBL2 is named in the same sentence as 65 diseases in open-access papers, as found by Europe PMC text mining. Sharing a sentence is not in itself a finding about the gene and the disease. The quoted sentences say what the papers report.
retinoblastoma (13 papers, 2013 to 2025). A malignant tumor that originates in the nuclear layer of the retina. "The number and type of somatic copy number alterations spontaneously acquired during retinoblastoma development suggest Rb1/Rbl2 deficient murine retinoblastomas are more like their human counterparts." (PMID 35368709, 2022). "Ablation of Rb1/Rbl2 leads to rapid development of multifocal retinoblastoma while ablation of Rb1/Rbl1 causes more delayed development of unifocal retinoblastoma." (PMID 35368709, 2022). "Experimental evidence implicating RBL1 and RBL2 in tumor suppression has roots in attempts to model retinoblastoma in mice." (PMID 35368709, 2022). "This reflects the expression pattern observed in native retinoblastoma with prominent expression of RBL1 but almost undetectable expression of RBL2, further reinforcing the validity of the retinal organoid model." (PMID 35565295, 2022). "The retinoblastoma tumor suppressor family contains the proteins, pRb, p107, and p130, encoded by the RB1, RBL1, and RBL2 genes, respectively." (PMID 35250950, 2022). "Its overexpression in high-grade serous ovarian cancer correlates with reduced retinoblastoma tumor suppressor RBL2 and leads to faster growth and poor differentiation of tumor cells." (PMID 28750689, 2017). "Other copy number changes reported in retinoblastoma include gains of DDX1, MDM4 and OTX2, and loss of BCOR and RBL2." (PMID 29124525, 2017). "Recent studies have also implicated KDM6A as a candidate tumor suppressor gene whereby ectopic expression leads to enhanced expression of the RB (retinoblastoma) and RBL2 (retinoblastoma-like 2) genes." (PMID 23658530, 2013). "Furthermore, aside from presenting low levels of RB1 expression, retinoblastoma cells show low levels of the mRNAs for the RB1 paralog RBL2, suggesting that the G1/S restriction point is severely impaired." (PMID 38332874, 2024). "To investigate whether the accumulation of DNA DSBs also operates in vivo to impede tumor growth, we studied retinoblastoma development in chimeric mice generated by blastocyst injection of Rb-/-Rbl2-/-embryonic stem cells (ESCs)." (PMID 30322449, 2018). "Importantly, RBL2/p130 is often lost in both retinoblastoma and PB as part of chr 16q deletion." (PMID 40075567, 2025). "Besides tumor initiation by biallelic loss of the RB1 gene, cytogenetic analysis has identified recurrent copy number variants (CNVs) in retinoblastoma tumors, leading to the proposal of several candidate driver genes other than RB1 such as KIF14, MYCN, DEK, E2F3, RBL2/p130, and NGFR." (PMID 33466343, 2021).
breast carcinoma (10 papers, 2001 to 2025). "We first identified human breast cancer lines with mutations in the RBL2 gene likely to decrease the protein expression using the Catalogue of Somatic Mutations in Cancer (COSMIC) database." (PMID 38678032, 2024). "This highlights significance of mutations in the pocket domain of Rbl2 gene in breast cancer, and also strengthen the supposition that K1083 acetylation is pre-requisite for its phosphorylation." (PMID 35385527, 2022). "This suggests that loss of Rbl2 expression is a frequent phenomenon in breast cancer pathogenesis." (PMID 26271034, 2015). "Current study was designed to screen genetic alterations within pocket domain and C-terminus (Exon 19–22) harbouring acetylation hotspots and NLS of Rbl2 proteins in breast cancer patients." (PMID 35385527, 2022). "In view of these circumstantial evidence, it is persuasive to thoroughly analyse acetylation and phosphorylation status of Rbl2 proteins in breast cancer patients, to fully understand the disease aetiology." (PMID 35385527, 2022). "Heightened mTORC2 downstream targets augmented quiescent CTCs (Ki67−/RBL2+ cells) in paired breast cancer tissues, along with high mTORC2 activity in solitary BMRCs and tissue-resident CTCs." (PMID 32575420, 2020). "This highlights not only the significance of Rbl2/p130 expression as an early prognostic tool for breast cancer pathogenesis but also suggests its involvement in tumor progression." (PMID 26271034, 2015). "Several basal B type breast cancers, such as HCC150082 and Cal-5183, harbour RBL2 loss of heterozygosity (LOH) mutations induced by a frameshift in the gene product and have reduced expression of RBL2 protein." (PMID 38678032, 2024). "Data mining revealed that RBL2 is more commonly gaining insertions and deletions in breast cancer than RBL1 and pRb, indicating that 275 out of 997 breast tumours had aberrations in the RBL2 locus whereas the corresponding numbers for RBL1 and pRb were 165 and 249, respectively." (PMID 38678032, 2024). "Next, we wished to learn whether RBL2 could control the transcription of WNT growth factors in breast cancer cells." (PMID 38678032, 2024). "This highlights the importance of Rbl2/p130 promoter methylation in breast cancer pathogenesis." (PMID 26271034, 2015). "Our results reflect an epigenetic regulation of Rbl2/p130 expression in breast cancer." (PMID 26271034, 2015). "The presence of RBL2 loss of function in aggressive breast cancer subgroups and pancreatic cancer with the associated increase in WNT pathway components prompted us to test if RBL2 could regulate the activity of the WNT pathway in human breast and pancreatic tumours." (PMID 38678032, 2024). "We found that the RBL2/E2F-WNT axis regulates the stem cell-like characteristics of CSCs in pancreatic cancer and breast cancer including self-renewal and expression of CSC markers, chemoresistance and invasive capacity." (PMID 38678032, 2024). "To further explore the impact of RBL2 on breast cancer CSC proliferation, we collected media from RBL2-LOH cancer cells and from the same lines stably overexpressing RBL2." (PMID 38678032, 2024). "We observed similar effects in oestrogen receptor-positive breast cancer, and analysis of patient datasets suggested CBX2 inhibits RBL2 activity in other cancer types." (PMID 35884550, 2022). "In human breast tumor tissues, mRNA levels of EIF2Ak2, USP18, DDX58, RBL2, STAT2, PGR, S1000A9, and CCND1 were significantly higher in ER+- than in ER--breast cancer tissues." (PMID 29416786, 2018). "Our results indicated that the RBL2/E2F-WNT can signal through paracrine mechanisms to induce fibroblast proliferation, which could contribute to fibrosis in PDACs, breast cancers and other cancer types." (PMID 38678032, 2024).
breast carcinoma (continued). "E2F1 and E2F4 induce whereas pRb/RBL2 reduce WNT ligand expression (e.g. WNT7A, WNT7B, WNT10A, WNT4) thereby regulating self-renewal, chemoresistance and invasiveness of CSCs in both PDAC and breast cancer, and fibroblast proliferation." (PMID 38678032, 2024). "For example, human RBL2 mutant T lymphocytes proliferate normally and exhibit normal immune function due to RBL1 upregulation, an upregulation also detected upon RBL2 knockdown in human breast cancer cell lines, suggesting a negative feedback loop." (PMID 28704371, 2017).
ovarian carcinoma (10 papers, 2012 to 2025). A malignant neoplasm originating from the surface ovarian epithelium. "Retinoblastoma‐like protein 2 (RBL‐2) has been described as a target of miR‐106a in ovarian cancer." (PMID 29845714, 2018).
pancreatic cancer (10 papers, 2018 to 2025). "Since little is known about the status of RBL2 in pancreatic cancers, we focused on RBL2 and characterised the mutation and expression status of RBL2 in PDACs." (PMID 38678032, 2024). "The DNMT1/RBL2/c-Myc axis is involved in the inhibitory effect of HOXB9 on pancreatic cancer cell proliferation by blocking cell cycle progression." (PMID 37301547, 2023). "HOXB9 inhibits the proliferation of pancreatic cancer cells by blocking cell cycle progression through the DNMT1/RBL2/c-Myc axis." (PMID 37301547, 2023). "For example, in pancreatic cancer miR-17-5p enhance its proliferation by disrupting RBL2/E2F2-repressing complexes." (PMID 34778021, 2021). "Furthermore, miR-17-5p, which is upregulated in pancreatic cancer, functions as an oncogene by directly targeting RBL2 expression." (PMID 31938022, 2020). "RBL2 and c-myc were essential for HOXB9 to inhibit pancreatic cancer cell proliferation." (PMID 39337523, 2024).
lung carcinoma (7 papers, 2012 to 2022). "AKT inhibition increased RBL2 expression and triggered apoptosis in both lung cancer and mesothelioma cell lines." (PMID 34487971, 2021). "Notably, in lung cancer and mesothelioma cells, both characterized by high AKT activity, AKT inhibition prevented Ser941 RBL2/p130 phosphorylation and was associated with increased RBL2/p130 levels and stability, suggesting a role for AKT in inhibiting RBL2/p130 function." (PMID 30652113, 2018).
Obesity (7 papers, 2011 to 2023). Accumulation of substantial excess body fat. "RBL2 plays a role in preadipocyte proliferation and differentiation and it has been suggested that a variant in the FTO gene is strongly associated with obesity and influences RBL2 expression, which impacts obesity risk." (PMID 34399688, 2021). "Also, mRNA levels of RBL2, that was suggested to mediate the biological consequences of a FTO variant on obesity risk, remained unchanged." (PMID 21687707, 2011).
breast tumor (6 papers, 2012 to 2024). "The relative expression of Rbl2/p130 in breast tumors was found to be significantly lower (P = 0.001) than control samples in all age groups." (PMID 26271034, 2015). "Using quantitative real-time RT-PCR, gene expression levels of Rbl2/p130 were determined in breast tumors and adjacent control tissues." (PMID 26271034, 2015). "Promoter methylation status in breast tumors, adjacent normal tissues and blood from the same patients along with control blood samples were analyzed to correlate the effect of methylation with down regulation of RbL2/p130 gene in breast cancer patients." (PMID 26271034, 2015). "Our findings corroborate with these reports and tells another aspect of the same story; significant decrease (P = 0.001) in Rbl2/p130 expression in breast tumors tissues irrespective of patient’s age." (PMID 26271034, 2015).
Burkitt lymphoma (4 papers, 2009 to 2019). A rare form of malignant mature B-cell non-Hodgkin lymphoma. "In the present study, we have analyzed pRb2 expression and searched for RBL2 mutations in endemic Burkitt lymphoma from Uganda." (PMID 19691827, 2009). "In Burkitt lymphoma (BL) subtype with RBL2/p130 mutation, the BTG1 expression is suppressed, resulting in loss of growth control." (PMID 30350856, 2019). "However, altered subcellular localization of pRb2 and mutations in the pRb2-encoding gene RBL2 have been described for some tumours, including Burkitt lymphomas (BL)." (PMID 19691827, 2009). "Reintroduction of wild-type RBL2/p130 into Burkitt’s lymphoma cell lines, which carry a mutated nonfunctional form of RBL2/p130, upregulated the expression of CGRRF1 and regained growth control." (PMID 31801577, 2019). "However, somatic mutations in RBL2 were observed previously only in primary nasopharyngeal carcinomas, lung tumors, and Burkitt's lymphomas but not in HCC." (PMID 28639733, 2017).
glioblastoma (3 papers, 2015 to 2021). The most malignant astrocytic tumor (WHO grade IV). "PRKCG and WEE1, when upregulated, are known to be good prognostic markers in Glioblastoma, while high mRNA levels of RBL2 are known to be associated with HPV+ head and neck tumors." (PMID 34796107, 2021). "Delivery of wild-type Rbl2/p130 gene may revert malignant phenotype in various cancer types including human cervix carcinoma (C33A); T98G human glioblastoma; nasopharyngeal carcinoma and Saos-2 human osteosarcoma cells." (PMID 26271034, 2015).
non-small cell lung carcinoma (3 papers, 2011 to 2023). A group of at least three distinct histological types of lung cancer, including non-small cell squamous cell carcinoma, adenocarcinoma, and large cell carcinoma.
atherosclerosis (2 papers, 2021 to 2023). A disease characterized by the build-up of fatty material and calcium deposition in the arterial wall resulting in partial or complete occlusion of the arterial lumen. "In addition, genes predicted to be targeted by the miR-17-5p, not previously associated with atherosclerosis, include ARID4B, E2F, GATA1, MEF2D, NR1I2, PURA, and RBL2." (PMID 36859458, 2023).
leiomyosarcoma (2 papers, 2018 to 2019). An uncommon, aggressive malignant smooth muscle neoplasm, usually occurring in post-menopausal women. "Consistent with this expectation, an integrative genome and transcriptome analysis of leiomyosarcoma applied TelNet for the TMM annotation and identified recurrent mutations in RBL2 (RB transcriptional corepressor like 2) and SP100 (SP100 nuclear antigen) as linked to ALT." (PMID 29776332, 2018). "These tumors lacked PRC2 (EED, SUZ12) mutations, and no mutations were present in RBL2 or SP100, two altered telomere maintenance genes found to be enriched in ALT-positive leiomyosarcomas." (PMID 31462295, 2019).
lymphoma (2 papers, 2014 to 2024). A malignant (clonal) proliferation of B- lymphocytes or T- lymphocytes which involves the lymph nodes, bone marrow and/or extranodal sites. "RBL2 disregulation has been recently associated with many types of lymphoma." (PMID 25170874, 2014). "RBL2 belongs to the retinoblastoma protein family and is repressed by PRMT5 in lymphoma cells." (PMID 39478125, 2024).
mesothelioma (2 papers, 2021). A usually malignant and aggressive neoplasm of the mesothelium which is often associated with exposure to asbestos. "Our laboratories have recently demonstrated that RBL2/p130 is a direct AKT target and mediates apoptosis induced by AKT inhibition in lung cancer and mesothelioma cells." (PMID 34638509, 2021).
osteosarcoma (2 papers, 2015). A usually aggressive malignant bone-forming mesenchymal neoplasm, predominantly affecting adolescents and young adults. "Moreover, RBL2/p130 overexpression induced apoptosis in Saos-2 osteosarcoma cells and marrow stromal cells committed toward a neuron-like phenotype and caused an increase in γ-radiation-induced apoptosis in hamster glioblastoma cells." (PMID 26160835, 2015).
small cell lung carcinoma (2 papers, 2022 to 2025). Small cell lung cancer (SCLC) is a highly aggressive malignant neoplasm, accounting for 10-15% of lung cancer cases, characterized byrapid growth, and early metastasis. "The Rbl1-deleted small cell lung cancers exhibited a higher rate of mediastinal lymph node metastasis and lymphocyte infiltration compared to Rbl2-ablated mice." (PMID 35368709, 2022). "Thus Rbl1 and Rbl2 have tumor suppressor activity in the context of small cell lung cancer, but it is only revealed in the absence of RB1." (PMID 35368709, 2022).
Cerebellar atrophy (1 paper, 2025). Cerebellar atrophy is defined as a cerebellum with initially normal structures, in a posterior fossa with normal size, which displays enlarged fissures (interfolial spaces) in comparison to the foliae secondary to loss of tissue. "In addition, cerebellar atrophy was noted in most RBL2 patients." (PMID 39692517, 2025).
developmental delay (1 paper, 2025). "We found that Drosophila Rbf LOF mutants recapitulate several features of patients harbouring RBL2 variants, including developmental delay, alterations in head and brain morphology, locomotor defects and perturbed sleep." (PMID 39692517, 2025).